PVALB (parvalbumin)
Diseases named in the same sentence as PVALB in open-access papers (continued):
Sharing a sentence is not in itself a finding about the gene and the disease.
autism spectrum disorder (22 papers, 2016 to 2026). A spectrum of developmental disorders that includes autism, and Asperger syndrome. "Parvalbumin-positive (PV+) interneuron dysfunction is believed to be linked to autism spectrum disorder (ASD), a neurodevelopmental disorder characterized by social deficits and stereotypical behaviors." (PMID 40164568, 2025). "Mouse models with evidence of parvalbumin (PV) alterations and associated changes in electrophysiology and occurrence of autism spectrum disorder (ASD)-like behavior." (PMID 33390904, 2020). "For example, “bipolar depression”, “autism spectrum disorder”, and “parvalbumin-positive interneurons” were primarily studied between 2010 and 2014." (PMID 40548058, 2025). "Abnormalities of parvalbumin expression and dysregulated GABAergic inhibitory input onto pyramidal output neurons have been described in at least some presentations of autism spectrum disorder." (PMID 34439901, 2021). "A reduction of the number of parvalbumin (PV)-immunoreactive (PV+) GABAergic interneurons or a decrease in PV immunoreactivity was reported in several mouse models of autism spectrum disorders (ASD)." (PMID 26819149, 2016). "This is supported by recent research showing that the parvalbumin‐expressing GABA interneurons are not eliminated in a mouse model of autism spectrum disorder and the downregulation of the parvalbumin protein expression is the cause of the apparent cell loss." (PMID 39626233, 2025). "Moreover, imbalanced E/I ratios are one of the major biological characteristics of human autism spectrum disorders, in which the number of parvalbumin-expressing interneurons and the GABA concentration in the cerebral cortex are reduced." (PMID 30166546, 2018). "Finally, the network of parvalbumin+ fast-spiking interneurons has attracted much interest in autism spectrum disorders (ASDs), and parvalbumin knockout mice exhibit behavioral phenotypes resembling core symptoms of the diseases." (PMID 28848395, 2017). "Mice with reduced (parvalbumin+/−) or absent (parvalbumin−/−) parvalbumin expression levels show behavioral deficits related to human autism spectrum disorder core symptoms." (PMID 38698428, 2024).
Allergy (18 papers, 2012 to 2026). An allergy is an immune response or reaction to substances that are usually not harmful. "Fish allergy, mainly caused by Parvalbumin (PV), is a worldwide health issue with few effective mitigation options." (PMID 41976553, 2026). "A large variety of commonly consumed fish species contain PVALB proteins which are known to cause fish allergies." (PMID 36672964, 2023). "Both severe fish and peach allergy are caused by a single major allergen, parvalbumin (Cyp c 1) and lipid transfer protein (Pru p 3), respectively." (PMID 22409908, 2012). "In the context of allergies, the major fish allergen parvalbumin was observed to be more abundant in farmed Sparus aurata compared to their wild counterparts." (PMID 38674116, 2024). "As illustrative examples of our gene identification system, we systematically analyze all parvalbumin genes in two common allergy-inducing species in Japan: red seabream (Pagrus major) and chum salmon (Oncorhynchus keta)." (PMID 39457461, 2024). "To additionally explain this new gene nomenclature system, we here identify all parvalbumin genes present in the genomes of two fish species that are common sources of fish allergy in Japan: red seabream (Pagrus major) and chum salmon (Oncorhynchus keta)." (PMID 39457461, 2024). "Since the PVALB gene plays an important role in the initiation of allergic reactions, it has been used for decades to develop alternate assays for fish identification." (PMID 36672964, 2023). "For optimal preparation of these extracts, collecting material from the dorsal-rostral part of the fish is recommended in case of suspicion of a parvalbumin allergy." (PMID 32712803, 2022). "An allergy to enolase and aldolase is less likely because of their heat instability; an allergy to parvalbumin is unlikely since swordfish is a fish species low in parvalbumin." (PMID 32712803, 2022). "The case of a patient with immediate-type allergy to L. niloticus indicating species-specific sensitization towards potential allergens of this species, other than parvalbumin (the most frequent allergen in fish) has been reported." (PMID 35681319, 2022). "Fish allergy is an immune reaction to allergenic proteins in the fish muscle, for instance parvalbumin (PV), considered the major fish allergen." (PMID 36359146, 2022). "The allergen parvalbumin (Gad c1) was positive, making an allergy to the majority of the fish species (cluster A) seem plausible given the cross-reactivity." (PMID 32712803, 2022). "Considering these diagnostics, an allergy to the salmon-specific parvalbumin epitope (cluster B) seems most plausible." (PMID 32712803, 2022). "The previous has been demonstrated with carp parvalbumin, and it represents a promising route for the development of fish allergy vaccines and subcutaneous specific immunotherapy." (PMID 33477460, 2021). "Recently, passive immunisation’s effectiveness via blocking antibodies created with hypoallergenic recombinant parvalbumin has been trialled in murine models of fish allergy." (PMID 33477460, 2021). "Frog allergy is rare and is a response to a parvalbumin that cross reacts with other parvalbumins found in fish that are the cause of more common fish allergies (due to shared cross-reactive IgE epitopes between the proteins)." (PMID 33761048, 2021). "The present study revealed that the rate of collagen allergy was higher than that of parvalbumin in dogs and collagen induced a stronger reactivity than that induced by parvalbumin based on the levels of specific IgE in these animals." (PMID 32938440, 2020). "Parvalbumin has a higher allergenic potency than collagen in humans with cod allergy." (PMID 32938440, 2020). "These species-specific allergies were triggered by allergens other than parvalbumin." (PMID 30402610, 2017). "Most patients with fish allergy have specific IgE antibodies against parvalbumin." (PMID 30402610, 2017).
Allergy (continued). "Of note, the rate of tropomyosin allergy was higher than those of parvalbumin or collagen allergies in dogs and the levels of specific IgE to tropomyosin was higher than those to other allergenic components derived from cod, such as parvalbumin and collagen, in dogs with cod allergy." (PMID 32938440, 2020). "A similar trend was observed in the context of fish allergies, wherein BAT with crude fish extracts outperformed BAT using purified parvalbumin." (PMID 40572728, 2025). "Conversely, some parvalbumin-negative patients appear to show IgE antibodies against fish enolase (47%) and aldolase (41%), which are relatively related to species-specific allergies to fish." (PMID 37763770, 2023). "Of note, it appears that IgE sensitization for different fish species based on parvalbumin does not correlate well with the reported clinical allergy or tolerance of the patient." (PMID 32712803, 2022). "In contrast, one study described a patient with an isolated allergy to swordfish whose IgE antibodies bound to a swordfish specific allergen but not to parvalbumin." (PMID 25225608, 2014). "The positivity of specific IgE for parvalbumin does not always succeed in discriminating patients with allergy to a single fish species from those with multiple fish allergies, as they are often cross-reactive between homologs, not necessarily implying a clinical reactivity." (PMID 37763770, 2023).
psychosis (16 papers, 2017 to 2025). "Particularly, dysfunction of parvalbumin positive inhibitory interneurons was linked to increased cerebral blood volume in mouse models of psychosis." (PMID 37891246, 2024). "Additionally, a loss of parvalbumin (PV)-positive interneurons in the hippocampus has been reported in post-mortem studies of psychosis patients and in rodent models used to study psychosis." (PMID 37511346, 2023). "Indeed, amygdala hyperresponsivity has been shown in a neurodevelopmental model of psychosis, in which a functional loss of parvalbumin interneurons in the hippocampus is associated with increased dopaminergic activity in the striatum." (PMID 33722617, 2021). "Task related gamma oscillations generated by synchronised activity in the cortical pyramidal cells (orchestrated by parvalbumin-positive inhibitory interneurons) are shown to be consistently diminished in psychotic disorders, as measured by EEG studies." (PMID 38710421, 2024). "Decreases in parvalbumin-expressing interneurons have been reported in rodent models of psychosis, as well as in patients with psychosis and AD." (PMID 37108357, 2023). "There is one study investigated whether METH dependence and psychosis may involve an effect on DNA methylation of the parvalbumin (PVALB) promoter." (PMID 40230379, 2025). "The parvalbumin (PV)-containing subgroup of GABAergic neurons is particularly affected in schizophrenia and METH-induced psychosis." (PMID 40230379, 2025). "Given that gamma oscillations are essential for cognitive processes and rely on effective parvalbumin positive interneuron function (Buzsáki and Wang, 2012), abnormalities observed in these frequency bands may explain the cognitive symptoms experienced in psychosis." (PMID 38710421, 2024).
bipolar disorder (15 papers, 2010 to 2026). A disorder of the brain that causes unusual shifts in mood, energy, activity levels and the ability to carry out day-to-day tasks. "Second, parvalbumin interneurons were enriched in bipolar disorder (and SCZ)." (PMID 38233398, 2024). "In addition, a significant decrease in parvalbumin-immunoreactive neurons in the entorhinal cortex of patients with bipolar disorder compared with control subjects has been observed." (PMID 26578879, 2015).
Parkinson disease (10 papers, 2019 to 2026). A progressive degenerative disorder of the central nervous system characterized by loss of dopamine producing neurons in the substantia nigra and the presence of Lewy bodies in the substantia nigra and locus coeruleus. "We investigated the alterations of hippocampal and reticulo-thalamic (RT) GABAergic parvalbumin (PV) interneurons and their synaptic re-organizations underlying the prodromal local sleep disorders in the distinct rat models of Parkinson’s disease (PD)." (PMID 34445628, 2021). "Parvalbumin interneurons in the dorsal striatum lose primary cilia in mice and humans harboring Parkinson’s disease–associated, activating mutations in LRRK2 kinase, resulting in loss of hedgehog signaling and decreased production of neuroprotective Neurturin to support dopamine neurons." (PMID 39537338, 2025). "Applying this technology to GPe parvalbumin-expressing neurons in a mouse model of Parkinson's disease, we discovered evidence for an upregulation of the oxygen homeostasis maintaining pathway involving Hypoxia-inducible factor 2α." (PMID 33188066, 2020).
Stroke (10 papers, 2016 to 2026). Sudden impairment of blood flow to a part of the brain due to occlusion or rupture of an artery to the brain. "It has been shown that daily motor rehabilitation in stroke mice triggers an improvement of grasping abilities, which is associated with a reduction in parvalbumin, calretinin, and calbindin expression in the agranular cortex adjacent to the infarct." (PMID 27897203, 2016). "The modulation of GABAergic activity plays a central role in facilitating functional recovery after stroke and we recently showed the association between T2D-induced cellular atrophy of GABAergic neurons positive for parvalbumin (PV) with poor functional stroke recovery." (PMID 34937562, 2021). "Moreover, we recently showed that impaired stroke recovery in T2D may also be associated with increased atrophy of striatal GABA-ergic parvalbumin (PV)+ interneurons, suggesting diminished neuroplasticity in striatum." (PMID 32447613, 2021). "Pharmacological enhancement of parvalbumin interneuron function improves motor recovery after stroke, reproducing rehabilitation recovery." (PMID 40089466, 2025). "Here authors identify parvalbumin interneurons as a key mediator of rehabilitation-induced stroke recovery and a drug targeting these neurons as a potential therapy." (PMID 40089466, 2025). "Stroke-projecting neurons show decreased dendritic spine density, reduced external synaptic inputs, and a lower proportion of parvalbumin synapse in the total GABAergic input." (PMID 40089466, 2025). "Mechanisms involved in neurovascular damage in the post-stroke recovery phase, i.e. neuroinflammation, impaired angiogenesis and cellular atrophy of GABAergic parvalbumin (PV)+ interneurons were assessed by immunohistochemistry/quantitative microscopy." (PMID 34937562, 2021). "Here, we show that neuronal circuits formed by presynaptic parvalbumin interneurons and stroke-projecting neurons mediate neurorehabilitation-induced recovery through network synchronization which provide molecular drug targets reproducing rehabilitation effects." (PMID 40089466, 2025). "Furthermore, gamma oscillation, a parvalbumin-regulated rhythm, is increased with rehabilitation-induced recovery in animals after stroke and stroke patients." (PMID 40089466, 2025). "Co-labelling of parvalbumin (PV) and Kv3.1 with WFA indicated that stroke reduced the expression of PNNs in the ipsilesional motor cortex L5 at 7 DPI." (PMID 37658339, 2023).
status epilepticus (7 papers, 2017 to 2025). Status epilepticus is defined as a continuous seizure lasting more than 30 min, or two or more seizures without full recovery of consciousness between any of them. "In the present study, status epilepticus (SE) evoked excessive mitochondrial fission in parvalbumin (PV) cells (one of GABAergic interneurons) and abnormal mitochondrial elongation in CA1 neurons in the rat hippocampus." (PMID 30233331, 2018). "Here, we examined the contribution of neuropsin–NRG1 signaling to the pathological functions of ErbB4-expressing, parvalbumin-positive GABAergic interneurons in the kainate (KA)-induced status epilepticus mouse model." (PMID 28267150, 2017). "We also observed co-localization of GFP with the interneuron marker Parvalbumin (PV) and occasional co-localization of GFP with the microglial marker CD11b at later time-points after status epilepticus (24 h)." (PMID 28235423, 2017). "On the other hand, translocation of high mobility group box 1 (HMGB1) and active caspase-3 into mitochondria is involved in apoptosis of parvalbumin (PV) cells (one of the GABAergic interneurons) and necrosis of CA1 neurons in the rat hippocampus, respectively, following status epilepticus (SE)." (PMID 33668863, 2021).
ischemia (6 papers, 2014 to 2025). A hypoperfusion of the BLOOD through an organ or tissue caused by a PATHOLOGIC CONSTRICTION or obstruction of its BLOOD VESSELS, or an absence of BLOOD CIRCULATION. "Here, we found that induction of ischemia resulted in loss of parvalbumin (PV) gamma-aminobutyric acid (GABAergic) neurons more than Ca2+/calmodulin-kinase II (CaMKII) glutamatergic neurons in the mouse cortex." (PMID 35406741, 2022). "This suggested that the loss of parvalbumin-positive neurons occurred in the early stage of ischemia, and NOBM treatment could reverse the reduction." (PMID 40337954, 2025). "Finally, the ischemia + hypothermia 120 h group also showed complete recovery of GAD+ and parvalbumin+ interneurons, but a significant loss of calbindin+ interneurons." (PMID 36835117, 2023). "By contrast, the ischemia + hypothermia 48 h group showed significantly higher densities of GAD+ (p = 0.0003) and parvalbumin+ (p = 0.0006) interneurons, but not calbindin+ (p = 0.8831) interneurons, compared with cell densities in the ischemia + normothermia group." (PMID 36835117, 2023).
temporal lobe epilepsy (6 papers, 2015 to 2025). A localization-related (focal) form of epilepsy characterized by recurrent seizures that arise from foci within the temporal lobe, most commonly from its mesial aspect. "Parvalbumin-expressing interneurons have been found to be particularly vulnerable in human temporal lobe epilepsy and in animal models." (PMID 40282228, 2025). "High expression of TLR8 in parvalbumin-interneurons may contribute to their high vulnerability in human temporal lobe epilepsy." (PMID 35507634, 2022). "In some pathological contexts, such as temporal lobe epilepsy and TBI as well as in another different model of acquired epilepsy, parvalbumin interneurons are known to be very sensitive to death and their loss is involved in the dentate gyrus hyperexcitability triggered by aberrant sprouting." (PMID 30804751, 2019).
Cerebral ischemia (5 papers, 2020 to 2025). Restriction of arterial blood supply to the brain associated with insufficient oxygenation to support the metabolic requirements of the tissue. "In addition, five proteins are shown to bind to neuroinflammation and cerebral ischemia, including parvalbumin alpha, superoxide dismutase, S‐adenosyl‐l‐homocysteine hydrolase, 3‐mercaptopyruvate sulfurtransferase, and cathepsin S." (PMID 38376040, 2024). "We investigated whether quercetin can regulate parvalbumin expression in cerebral ischemia and glutamate toxicity-induced neuronal cell death." (PMID 33632310, 2021). "Nitric oxide (NO), which is also actively produced during cerebral ischemia, showed a corresponding modulation: expression of all three CaBPs was associated with lower NO production in GAD65/67(+) neurons under OGD conditions, with parvalbumin showing the strongest inverse correlation." (PMID 40869287, 2025). "In the present study, cerebral ischemia in near-term fetal sheep was associated with a pattern of parasagittal cortical damage after 7 days of recovery, which included a marked reduction in the survival of cortical GAD+, parvalbumin+, calretinin+, and calbindin+ interneuron populations." (PMID 32899855, 2020).
cognitive decline (5 papers, 2017 to 2026). "It seems this crucial role impairs the sodium channel subunit Nav1.1; this is particularly prevalent in interneurons expressing parvalbumin, which are associated with changes in network functioning and cognitive decline in transgenic mice modeling AD." (PMID 38474398, 2024). "In particular, we propose that an important proximal cause of cognitive decline in AD is failure of the adaptive function of pyramidal neurons to modify excitatory drive of fast spiking parvalbumin (PV) interneurons." (PMID 28440221, 2017). "Cerebrospinal fluid (CSF) candidate markers (CHI3L1, parvalbumin) and synaptic proteins (SNAP-25, neurogranin, β-synuclein) may help identifying patients at higher risk of cognitive decline." (PMID 41960777, 2026). "The reduction of NPTX2 that is correlated with cognitive decline implicates a pathophysiological mechanism – failure of the adaptive function of pyramidal neurons to modify excitatory drive of fast spiking parvalbumin (PV) interneurons- that could potentially be targeted for therapeutics." (PMID 32552841, 2020).
Dystonia (5 papers, 2017 to 2026). An abnormally increased muscular tone that causes fixed abnormal postures. "Animal studies showed that developmental delay in the maturation of parvalbumin interneurons causes dystonia in dtsz-mutant Syrian hamsters." (PMID 34440520, 2021). "Dysfunction of parvalbumin interneurons in the striatum may cause dystonia and OCD." (PMID 36437372, 2022). "In addition, impaired GABAergic functions have been found in other hyperkinetic movement disorders such as dystonia and Tourette syndrome, the latter showing reduced parvalbumin-expressing interneurons in the striatum." (PMID 40257019, 2025). "Injections of the parvalbumin interneuron inhibitor in the dorsolateral striatum elicit dystonia." (PMID 34440520, 2021). "Thus, disorders where parvalbumin interneurons fast spiking activity is involved such as dystonia could benefit from such neuroprotective effect." (PMID 28824383, 2017).